KRAS (KRas proto-oncogene, GTPase)
Diseases named in the same sentence as KRAS in open-access papers (continued):
Sharing a sentence is not in itself a finding about the gene and the disease.
tumor (continued). "KRAS-mutant allele-specific inhibitors, such as AMG 510 (sotorasib) and MRTX849 (adagrasib), can target G12C-mutant KRAS and suppress downstream signaling, thus killing tumor cells harboring KRASG12C mutations." (PMID 34858498, 2021). "Although it is a promising strategy to treat the patients with KRAS mutations, the “off-the-shelf” tumor vaccines cannot fulfill the clinical needs for those who do not harbor the mutations." (PMID 34484187, 2021). "Taken together, all this evidence suggests that KRAS mutations cannot be evaluated as a single entity, but it needs to be placed in the context of the specific tumor features and seen as part of a complex process in cancer development and progression." (PMID 35004317, 2021). "MGMT inactivation predisposes to alkylation-induced DNA damage, which is associated with G → A transition mutations in the KRAS oncogene, thus driving tumor growth." (PMID 33978766, 2021). "In this study, we obtained qualitative and quantitative information on the KRAS mutation subtypes in paired tumor tissues and blood and evaluated their function to predict prognosis with CA 19-9 levels." (PMID 34829828, 2021). "Recent evidence also appears to implicate PLEXIND1 in pathologic TGFβ signaling, which acts as a co-receptor to promote tumor growth and reduce E-cadherin expressing in tumor cells with oncogenic KRAS mutation." (PMID 34680235, 2021). "When comparing the patient collective of this work with the patient collectives of similar works, differences in tumor location and KRAS mutational status were found." (PMID 34638442, 2021). "Induction of mitochondrial dysfunction is an important mechanism by which KRAS signalling causes metabolic changes and ROS stress in cancer cells and promotes tumour development." (PMID 33941245, 2021). "Among the patients with a KRAS/BRAF tumor tissue mutation, KRAS/BRAF mutations were detected in plasma cfDNA in 93% of patients with CRC‐LM compared to 20% of patients with CRC‐PM (p < 0.0001)." (PMID 33635598, 2021). "Comparing with adjacent nontumorous tissue, CAC specimen showed a decreased MKNK2a level and an increased MKNK2b level, which were correlated with KRAS mutation and tumor size." (PMID 33602301, 2021). "At the time that amino acid glycine is mutated, KRAS protein acquires oncogenic properties that result in the tumor cell growth, proliferation, and cancer progression." (PMID 34901697, 2021). "Mutated KRAS can cause many changes in a significant molecular web covering several pathways, both as an inhibitor and as an activator of key molecules for tumor formation." (PMID 34781949, 2021). "The combination of sotorasib with anti-PD-1 determined complete regression in nine out of ten CT26 KRAS mutated colon carcinoma mice, which is one of the most immune-responsive mouse tumor models, and induced T cell memory." (PMID 33777798, 2021). "In this study we stratified tumor samples according to the KRAS mutation status, and found that Hh signaling and NF-κB were positively correlated only in tumors with KRAS mutation." (PMID 34046348, 2021).
tumor (continued). "Tyrosine kinase/Ras signaling is one of the main regulators of cell mechanics and an integral element in the reprogramming of normal cells into tumor cells upon KRAS mutation." (PMID 34298706, 2021). "Single-cell RNA sequencing of tumors reveals that KRAS ablation causes changes both in tumor cells and host immune cells." (PMID 33674596, 2021). "In fact, the neoplasia-specific epigenetic reprogramming was observed within two days after injury in KRAS-mutated pancreatic epithelial cells." (PMID 34023857, 2021). "Later on injection of intact KRAS in syngeneic mice caused tumor formation and survival for 2 weeks." (PMID 34781949, 2021). "Intriguingly, 4% of PDACs exhibit multiple KRAS mutations, and these different KRAS mutations appeared in distinct cancer cells in a single tumor." (PMID 34337294, 2021). "Tumor tissue is routinely used to search for KRAS or NRAS gene mutations that occur in around 55% of metastatic CRC (mCRC) and predict a lack of response to the EGFR-targeted monoclonal antibodies, such as cetuximab and panitumumab." (PMID 34638228, 2021). "Pharmacological inhibition of ISR potently impairs lung tumor growth with KRAS G12C as well as G12D, supporting a broader anti-tumor effect on cancers with different KRAS mutations." (PMID 34330898, 2021). "KRAS, the most frequently mutated oncogene in cancer especially in PC, was reported to rewire metabolism to support tumor growth." (PMID 34660806, 2021). "KRAS mutation was the prevalent mutated gene in this tumor type, with a mutation frequency of 74.57%." (PMID 33853586, 2021). "Anti-EGFR therapy was even associated with a detrimental effect in patients with KRAS mutant tumours." (PMID 34253874, 2021). "Together, these in vivo and in vitro experiments suggested that the anti-tumor effect of RGS was probably dependent on the presence of KRAS mutations." (PMID 34347396, 2021). "The median tumor mutational burden (TMB) in KRAS wild-type CRC (n = 534) and KRAS mutated CRC (n = 372) were 8.27 mutations/Mb, and 13.27 mutations/Mb, respectively." (PMID 33982211, 2021). "Tumor cells expressing mutated KRAS induce the production of cytokines, chemokines, and growth factors, mediating the remodeling of surrounding stroma cells." (PMID 34064352, 2021). "Mutationally activated KRAS in tumor cells reprograms macrophages to a TAM-like phenotype via a combination effect of tumor-derived CSF2 and lactate." (PMID 33833221, 2021). "The first of the strategies to address the treatment of KRAS-mutated tumours through metabolic modulation consists of interfering with glucose metabolism." (PMID 34359657, 2021). "A third KRAS G12C covalent inhibitor is JNJ-74699157 (ARS-3248), currently evaluated in a phase I clinical trial enrolling different KRAS G12C mutated tumor types (NCT04006301)." (PMID 35004317, 2021). "By performing single-cell ATAC-seq on over 6000 KRAS-mutated cells isolated from KRAS-mutated or KRAS-mutated plus injured conditions, the neoplasia-specific chromatin state was confirmed as bona fide chromatin remodeling." (PMID 34023857, 2021). "Subtyping based on genomic features, neoplasm-like, and KRAS-mutant stroma was associated with poor DFS." (PMID 34733795, 2021). "On the other hand, primary cultures represent all tumour grades and also different mutational status at least for KRAS." (PMID 33325631, 2021).
tumor (continued). "Combination treatment with oHSV and MEKi Trametinib enhanced virus replication mediated by down-regulation of STAT1 and PKR expression or phosphorylation in BRAF V600E-mutated tumor cells as well as BRAF wt/KRAS-mutated tumor cells." (PMID 34578339, 2021). "Sotorasib and adagrasib mediate selective tumor suppression activity across a panel of cancer cell lines harboring the KRAS-G12C mutation." (PMID 34607583, 2021). "KRAS amplification was implicated as the mechanism of resistance from crizotinib treatment in MET exon 14 mutant-NSCLC in a study using patient tumor-derived cells and xenografts, which was effectively targeted by dual MET/PI3K inhibition." (PMID 34660287, 2021). "Post-transcriptional regulation of PD-L1 mRNA stability is induced by KRAS activation, causing an upregulation of PD-L1 expression on tumour cells." (PMID 34944851, 2021). "Mutational profiling with KRAS and other prominent tumor-suppressor genes alone can increase the sensitivity by 56% and diagnostic yield to 100% when done in conjunction with cytology." (PMID 34868996, 2021). "Next‐generation sequencing analysis of the pretreatment FFPE tissue biopsies identified 78 tumor samples with mutations in KRAS (78%) and 22 with a non‐KRAS mutation (22%)." (PMID 34449963, 2021). "The protein encoded by the RASSF2 gene has been found to be a potential tumor suppressor and can act as a KRAS-specific effector protein." (PMID 34745226, 2021). "Kaplan–Meier analysis estimated that likelihood of survival was higher in patients with wild-type KRAS tumours (35%) than in mutated-type KRAS (14%) (median: 28 vs. 15, respectively) (P=0.001)." (PMID 34557315, 2021). "This patient-derived xenograft (PDX) mouse model maintained histological tumor features as well as genetic alterations, such as KRAS G12D mutation, with the original tumor." (PMID 34282753, 2021). "The frequency of smokers ≥30 pack-years (50.0%, 4/8) and smokers 0–30 pack-years (25.0%, 2/8) among patients with tumours having KRAS mutations was significantly higher than that among smokers 0 pack-years (6.5%, 5/77) (P=0.002)." (PMID 34804960, 2021). "Of the 419 patients evaluated, 178 patients (42%) met the selection criteria and carried a tumor tissue KRAS mutation." (PMID 34820593, 2021). "We also reported that dual p38 and MEK inhibition effectively impaired the tumor growth of KRAS-mutated NSCLC cells." (PMID 34885068, 2021). "This also reflected statistically lower time to progression (TTP) in patients having both mutations in KRAS and STK11 genes compared to the tumor with only KRAS mutations." (PMID 34164344, 2021). "A preclinical study of another oral, selective, small molecule (MRTX849) targeting KRAS G12C showed a broad spectrum of activity in tumours with the KRAS G12C mutation in in vivo models, resulting in significant tumour regression in most models." (PMID 34012925, 2021). "KRAS-mutated tumour cells can be killed by inhibiting other synergetic lethal genes responsible for their growth and survival." (PMID 34012925, 2021). "As the role of targeted therapy for the treatment of metastatic CRC has become essential, the NCCN Panel recommends the determination of tumor gene status for KRAS/RAS and BRAF mutations, as well as HER2 amplifications." (PMID 34598716, 2021). "In the chemotherapy cohort, the detection of KRAS tumor mutations was performed using the RASKET method and ddPCR in 22 patients." (PMID 34675229, 2021).
tumor (continued). "In the present study, somatic point mutations in KRAS appeared in a low frequency in both tumor and circulating DNA samples." (PMID 34203201, 2021). "The high tumor burden observed in our study makes the PI3K/mTOR signaling pathway an interesting potential druggable target for patients with KRAS A146–mutated tumors." (PMID 34820593, 2021). "It has been confirmed that the presence of tumor-infiltrating lymphocytes (TILs) is associated with improved overall survival, and the success of TILs in one patient with KRAS G12D mutation indicates the promise of adaptive immunotherapy in CRC patients." (PMID 34721435, 2021). "Patients with mCRC with a KRAS A146–mutated tumor represent a distinct molecular subgroup of patients with higher tumor burden that is associated with worse clinical outcomes." (PMID 34820593, 2021). "This study thus provides a conceptual framework to understand the tumor immune microenvironments of CRC in the context of KRAS mutation and treatment strategies designed to treat KRAS-mutant CRC patients." (PMID 33413474, 2021). "In our studies, therapeutic effectiveness was seen in syngeneic tumor mice with BRAF wt/KRAS-mutations." (PMID 34578339, 2021). "Recently, a STK11/LKB1 co‐mutation in KRAS‐mutant NSCLC was reported as a new predictive marker for tumor resistance to ICI therapy." (PMID 33655698, 2021). "It is becoming increasingly apparent that KRAS mutations manipulate signaling in both tumor cells and neighboring PSCs and influence the metabolic interactions between the two cell types." (PMID 33546284, 2021). "Novel TPD strategies are expected to serve as promising therapeutic methods for treating tumor patients with KRAS mutations." (PMID 34830024, 2021). "Since KRAS A146 mutations occur in roughly 4% of patients with mCRC, only a limited number of patients were available with a KRAS A146–mutated tumor despite the large number of patients included in the clinical trial." (PMID 34820593, 2021). "By contrast, activating mutations of the KRAS proto-oncogene can be identified in approximately 80-90% of PDAC patient tumours." (PMID 34956889, 2021). "Taken together, we conclude that mutationally activated KRAS in tumor cells triggers the functional reprogramming of macrophages via a combination effect of CSF2 and lactate." (PMID 33833221, 2021). "After ctDNA analysis, we retrospectively checked the RAS status of the smaller tumor and found the same KRAS mutation found in ctDNA." (PMID 34381078, 2021). "Regarding preclinical evidence, two previous compounds (ARS-853 and ARS-1620) have demonstrated to reduce cell growth and inhibit downstream signaling to MAPK exclusively in tumor cell lines with KRAS G12C mutations." (PMID 35004317, 2021). "KRAS itself remains undruggable despite advances in inhibitors for the KRASG12C mutation that demonstrated anti-tumor activity in clinical trials." (PMID 33691728, 2021). "Studies of multiple biopsies from various CRC sites have shown that over 65% of tumors have intra-tumor heterogeneity, and there was 10-30% heterogeneity in KRAS and BRAF mutations within tumors." (PMID 34888246, 2021). "Remarkable intratumor heterogeneity before chemotherapy was confirmed, where different KRAS mutation statuses between the tumor center region and the margin were detected with a high percentage of 44%." (PMID 34745987, 2021).
tumor (continued). "Patient sex, age, TNM stage, tumor location, treatment methods, histology, KRAS mutation, BRAF mutation, Fusobacterium nucleatum, mucin phenotype, and programmed death-ligand 1 (PD-L1) status were evaluated." (PMID 34797780, 2021). "Genetic ablation of STK11 in a KRAS-driven murine model of NSCLC demonstrated an accumulation of neutrophils with T-cell suppressive capacities associated with a decreased number of tumor-infiltrating lymphocytes and a reduced expression of PD-L1 in tumors." (PMID 34831355, 2021). "The trial will recruit patients with pathologically documented, previously treated NSCLC with evidence of the KRAS G12C mutation in the archived primary tumor tissue as confirmed through molecular testing." (PMID 34943432, 2021). "Beyond this sustained replication property, KRAS mutation also mediates autocrine effects and crosstalk with several components in the tumor microenvironment (TME), promoting inflammation and evading the immune response." (PMID 34064352, 2021). "EGFR and KRAS mutation status discordance between primary tumor and LCBM occurs in approximately 10% and 13% of patients, respectively." (PMID 35201504, 2021). "Patients with mCRC with a KRAS A146–mutated tumor showed a worse prognosis than patients with another KRAS mutation variant." (PMID 34820593, 2021). "In this study, the fail rate of tissue sampling was much lower, but there was still one clinically relevant mutation in KRAS detected in cfDNA corresponding to one of the insufficient tumor samples." (PMID 34217228, 2021). "The observation that right-sided CRC has a worse prognosis compared to the left-sided tumours has been described earlier, and KRAS and BRAF mutations have recently also been established as negative prognostic cancer markers." (PMID 33802849, 2021). "There is also evidence that KRAS mutations are involved in tumor cell evasion of host immune responses." (PMID 33513764, 2021). "Whole-exome sequencing of human PDAC or NSCLC tumors shows that, despite the genetic heterogeneity within the tumor, KRAS is mutated in different regions." (PMID 34607583, 2021). "In both patients, the index tumor presented KRAS mutations (12Val and 12Cys) and the companion one showed wildtype KRAS." (PMID 33671994, 2021). "The nude mouse xenograft tumor model was used to further validate the KRAS mutation-dependent PDAC tumor growth promoted by IL-1β, TNF-α, and Shh stimulation." (PMID 34046348, 2021). "In three patients (CRC152, CRC160, CRC164), tumor tissue showed variants in the same KRAS codon number as was seen in cfDNA analyzed by BEAMing and TST170; however, the specific variant identified was different between TST170 and tumor tissue." (PMID 34640513, 2021). "This trial included a lung cancer patient detected with KRAS mutation known for regulatory roles in tumor glutamine utilization and demonstrated significant Tumor Avidity for FGln." (PMID 35223460, 2021). "Among the 107 patients, 33 (30.8%) had a KRAS mutation in the primary tumor and 36 (33.6%) had a KRAS mutation in the corresponding CRLM." (PMID 33946899, 2021). "Our analysis demonstrates that stratifying groups of heterogeneous cancer models by three variables, in this case tumor type, KRAS mutation status and sex, reveals differentially essential genes." (PMID 34663427, 2021). "The SAA/ALOX5 ratio strongly correlated with TANs and was significantly increased in tumours harbouring an oncogenic KRAS mutation." (PMID 34203378, 2021). "Taken together, the results from the 66 CRC patients showed that SUVmax has little associations with the clinical features of CRC, KRAS mutation, tumor biomarkers, and Ki-67 index." (PMID 34956868, 2021). "In the multiple regression analysis, the factors that showed an independent prognostic value were KRAS mutation, N+ tumours, tumour grade of differentiation, ECOG 1-2 Index, and PCI." (PMID 34557315, 2021).